CASP1 (caspase 1)
Diseases named in the same sentence as CASP1 in open-access papers (continued):
Sharing a sentence is not in itself a finding about the gene and the disease.
tumor (continued). "Through IHC experiments, we found that CD44s, NLRP3, caspase-1, and IL1B were expressed in most tumor cells, and we demonstrated the positive relationship between CD44s and caspase-1 by quantifying IHC results." (PMID 33168816, 2020). "Our data demonstrated that Caspase 1 inhibition induces the release of VEGF and MMPs from tumor cells and stimulates endothelial cell tube formation." (PMID 33613529, 2020). "Consistent with this, in our immunohistochemical staining experiments, caspase-1 and IL-1β in RCC cancer tissues were stained more lightly than in non-tumor tissues." (PMID 32303673, 2020). "The cells were injected into the mammary fat pad of WT, Caspase-1 KO and Asc KO BALB/c mice, respectively, and tumor growth was monitored over time." (PMID 33042810, 2020). "Following tumor excision, IHC analysis was used to determine tumoral expression of apoptosis- and pyroptosis-related biomarkers, including NLRP3, IL-18, IL-1β, and caspase-1." (PMID 32209729, 2020). "Tumor tissue sections in the HRW groups presented moderate-to-strong positive expression of NLRP3, caspase-1 and GSDMD." (PMID 31924176, 2020). "Though tumor tissue sections in the HRW and NC groups presented moderate-to-strong positive expression of NLRP3, caspase-1 and GSDMD, the HRW group showed much higher staining by IHC." (PMID 31924176, 2020). "Increased protein expression of caspase-1, IL1β, and IL18 occurred in surface epithelium, tumor cells, and immune cells." (PMID 31923221, 2020). "Tumor tissue sections in the HRW group presented much higher NLRP3, caspase-1 and GSDMD staining by IHC." (PMID 31924176, 2020). "This study highlighted the capacity of PD-L1 to drive immunosuppression, through NLRP3 activation in tumor cells, MDSC recruitment and CD8+ T cells inhibition, without exploring the effects of therapy combining anti-PD-L1 with NLRP3/caspase-1 inhibitor." (PMID 33261061, 2020). "Next, we evaluated the levels of AIM2 in tumor tissues and found that luteolin administration significantly downregulated AIM2, caspase-1, and IL-1β expressions at mRNA levels." (PMID 30833546, 2019). "By contrast, MDSC originating from tumor-bearing mice treated by 5-FU and fed a DHA-enriched diet presented a lower caspase-1 activity." (PMID 31217433, 2019). "Several genes encoding core inflammasome components were all significantly expressed at higher levels in ACP tumours compared with control tissues, including NLRP1 (6.4-fold), NLRP3 (4.8-fold), NLRC4 (4.8-fold), CASP1 (5-fold) and PYCARD (4-fold) [Suppl." (PMID 29541918, 2018). "We next used immunohistochemical (IHC) staining to evaluate the protein expression levels of ASC, IL-1β, CASP1 and NLRP3 in tumor cells using a second cohort of OSCC biopsy samples (n=111)." (PMID 27367024, 2016). "Here, we show that the NLRP3 inflammasome-related proteins, ASC, IL-1β, CASP1, and NLRP3, are all highly expressed in OSCC tumor cells compared to adjacent normal cells." (PMID 27367024, 2016). "Caspase-1 KO mice had reduced lung metastasis three weeks after i.v. injection of EO771 cells, as indicated by number of tumor nodules and gross morphology of the lungs." (PMID 27786298, 2016). "Taken together these data imply that lung tumor lesions are populated by macrophages which pro-tumor activity is regulated by the activation of the NLRP3 inflammasome that leads to the release of IL-1α and IL-1β in a caspase-11/caspase-1-dependent manner." (PMID 27528423, 2016). "In conclusion, our data imply lung tumor lesions are populated by macrophages which pro-tumor activity is regulated by the activation of the NLRP3 inflammasome that leads to the release of IL-1α and IL-1β in a caspase-11/caspase-1-dependent manner." (PMID 27528423, 2016). "Ivermectin directly impacts the balance between ATP-dependent pro-survival and cytotoxic signals, converting a key pro-survival and tumor-promoting pathway into a P2X7- and caspase-1-mediated immunogenic cell death." (PMID 26552848, 2015).
tumor (continued). "MM tumor cells/tissues showed decreased levels of inflammasome components like NLRP3 and caspase-1 as compared to human mesothelial cells or normal tissue counterpart of tumor." (PMID 26689911, 2015). "Tumors in the Flii overexpressing mice had significantly decreased levels of early apoptotic markers annexin-V and pro-inflammatory caspase-1, potentially indicating reduced apoptosis occurring in these tumors which would increase SCC tumor progression." (PMID 26497552, 2015). "To investigate the effects of inflammasome signaling on tumor initiation and development, we used a modified well-established protocol to induced skin tumorigenesis on WT, ASC-KO and CASP-1-KO mice." (PMID 25268644, 2014). "IHC also showed that caspase-1, caspase-3, caspase-6, caspase-9, and PARP proteins were mainly expressed in the cytoplasm of tumor tissue." (PMID 24204937, 2013). "Immunofluorescence staining for cleaved-caspase-1 and GSDMD was employed to assess the killing effect of M@P on tumors, confirming that M@P could promote pyroptosis in tumor cells." (PMID 39743555, 2025). "Additionally, ZIF-8 nanoparticles induce pyroptosis in 4T1 cells via a caspase-1- GSDMD-dependent pathway, which activates antitumor immunity and reprograms the immunosuppressive tumor microenvironment, leading to effective tumor inhibition." (PMID 39994107, 2025). "IHC of tumor sections from mice receiving HOXC8 siRNA displayed strong caspase-1 but reduced Ki67 staining without alteration of cleaved caspase-3 levels, indicating that tumor suppression was due to pyroptosis." (PMID 40701951, 2025). "We also observed a higher level of CASP1 gene expression in patients without tumor cell infiltration into adipose tissue and without lymphovascular invasion." (PMID 40806590, 2025). "Furthermore, H2 diffusion to mitochondria induces an oxidative stress response, triggering pyroptosis through the canonical ROS/caspase-1/GSDMD pathway, enhancing tumor immunogenicity and activating T cell-mediated adaptive immune responses." (PMID 41402300, 2025). "Furthermore, CYP1B1 hinders apoptosis by inhibiting the activation of caspase-1 (CASP1) and downregulating pro-apoptotic DAPK1, thereby providing tumor cells with a survival advantage." (PMID 41155673, 2025). "In addition, TIM3 and caspase 1 expression were increased in tumor samples from Jurkat-TOXsg-tumor and Jurkat-TIM3-tumor related to Jurkat-sgControl -tumor, but caspase 3 levels were not changed in these three tumor tissues." (PMID 39080376, 2024). "As expected, caspase-1 did not affect IL1β gene expression, and because of the absence of paracrine stromal-tumor cell interaction, KBP cells grown in monolayer produced minimal IL1β9." (PMID 39353903, 2024). "Mice lacking ASC and caspase-1 showed an increased tumor burden related to attenuated levels of IL-1β and IL-18 in the site of the tumor." (PMID 39684769, 2024). "PCR results revealed a significant increase in the mRNA expression levels of caspase-1, caspase-11, NLRP3, and GSDMD in the transplanted tumor tissues when LINC00365 was downregulated, and western blot analysis revealed a significant increase in the expression of the corresponding proteins." (PMID 39439418, 2024). "In tumor tissues, IL-1α, IL-1β, IL1R1, IL1RL1, IL1F10, IL33, CASP1, and AIM2 are highly expressed." (PMID 39461030, 2024). "The top-scoring genes altered in the four gene sets included many genes associated with cell apoptosis and DNA damage, such as GADD45A, DDIT3, BAX, CASP1, CASP8, ATM, and FANCD2, demonstrating that diminishment of RAD51 contributes to the tumor suppressive effect." (PMID 37175611, 2023). "designed the novel pyroptosis inducer, Cu-TBB, which can specifically target the tumor cells and promote tumor cell pyroptotic death via the caspase-1/GSDMD pathway without damaging normal human cells and organs." (PMID 38016064, 2023).
tumor (continued). "Moreover, IL-17A-mediated mitochondrial dysfunction induces ROS-induced activation of the NLRP3 inflammasome and cleavage of caspase-1, driving pyroptosis and eventually promoting CD8 + T-cell infiltration into the tumour microenvironment." (PMID 37211606, 2023). "Pyroptosis is suppressed in MM tumor cells judged from the low expression of NLRP3 and caspase-1." (PMID 38016064, 2023). "Because TAMs can become lipid-accumulating and differentiate into a pro-tumorigenic phenotype as a result of activated Caspase-1, Caspase-1 inhibitors like NCX-4016, YVAD, and VAD can rewire TAMs into an anti-tumorigenic phenotype and stop tumor growth in vivo." (PMID 37138860, 2023). "IL-1β enhances tumor cell proliferation, migration and invasion while coculture of tumor cells with macrophages enhances the proliferation of tumor cells, which is AIM2 and caspase 1/11 dependent." (PMID 37449203, 2023). "Active caspase-1 directly cleaves GSDMD and induces pyroptosis in tumor cells." (PMID 35673561, 2022). "Therefore, we tested the effects of si-m/hVDAC1-B tumor treatment on the expression of NRLP3, activated caspase 1, and IL-1β." (PMID 35883451, 2022). "For example, in GKO mice, while bLF administration did not activate the IFN-γ/caspase-1/IL-18 effector pathway, it inhibited tumor growth and metastasis by activating the IFN-alpha/IL-7 effector pathway." (PMID 35264972, 2022). "We showed that deletion of NLRP3, but not AIM2, phenocopied caspase-1/IL-1β dependent tumor progression in vivo." (PMID 36439171, 2022). "Myeloid intrinsic caspase-1 activity maintains myeloid cell survival in tumor microenvironment without induction of immune cell trafficking to the tumor site." (PMID 36439171, 2022). "Mechanistically, both tumor control and anti-tumoral CD8+ T cell responses depended on enhanced inflammasome activation in Tmem176b−/− mice since they were reversed by IL-1β blockade and Casp1 deletion." (PMID 36340035, 2022). "Notably, the expression levels of 5 PRGs (CASP1, CASP3, CASP6, GSDMB, and GZMA) were lower in both CRC tissues and the high-stage group, suggesting that their potential function as tumor suppressors in CRC tumorigenesis and development." (PMID 35937993, 2022). "We found that myeloid intrinsic NLRP3-mediated activation of caspase-1 and subsequent IL-1β release is permissive towards tumor growth, and that caspase-1 regulates the survival but not trafficking of the myeloid cells to the TME." (PMID 36439171, 2022). "Western blot data showed that the HDSB11 administration inhibited NLRP3 and cyclin D1 protein expressions compared with the model group in tumor tissues and suppressed NLRP3, procaspase-1, and caspase-1 (p10) expressions compared with the control group in cells." (PMID 34239588, 2021). "DC activation by binding to ATP also promotes caspase-1 dependent NLRP3 inflammasome formation and the release of IL-1β, which in turn promotes CD8+ T cells and IL-17 producing-γδ T cell mediated anti-tumor response." (PMID 34263254, 2021). "To determine whether DDP-induced pyroptosis suppresses tumor growth and metastasis via MEG3/NLRP3/caspase-1/GSDMD pathway in vivo, we established a xenograft model of nude mice bearing the MDA-MB-231 cells." (PMID 34326697, 2021). "Likewise, the contact of tumor cells with P.CNF.1 and P.CNF.5, respectively, induced significantly increased (p < 0.01 and p < 0.0001, respectively) caspase-1 levels in a time-dependent manner." (PMID 34452150, 2021).
tumor (continued). "However, the contact of tumor cells with P.CNF.1 and P.CNF.5 led to a significant increase in caspase-1 production, compared with P.CNF.0 (p < 0.01 and p < 0.0001)." (PMID 34452150, 2021). "A minor group representing 30% (32/96) of CRCs, mainly MSS CRCs and only five MSI CRCs (i.e., 20% of MSI), displayed no or very low levels of active caspase-1 in tumor cells (<10% positive tumor cells, score 0–1)." (PMID 33430344, 2021). "The absence of caspase-1 significantly delayed tumor onset in mice suggesting a pro-tumoral role for the inflammasome." (PMID 33042810, 2020). "Therefore, we first analyzed mRNA expression of Caspase-1, PYCARD, and NLRP3 in paired normal and tumor tissues collected from CRC patients by qPCR experiments." (PMID 33102234, 2020). "For caspase-1 and IL18, the pattern of stained cells was similar in hen and human tumor tissue." (PMID 31923221, 2020). "Thus, BayK8644 restrains EG7 tumor growth in a TMEM176B-, caspase-1/11-, and CD8+ T cell-dependent manner, phenocopying Tmem176b−/− mice." (PMID 31085177, 2019). "We found that BayK8644 significantly improved survival of WT but not Casp1/11−/− tumor-bearing mice." (PMID 31085177, 2019). "Considering the caspase-1/PPARγ/MCDA axis as an important mechanism to improve TAMs differentiation and tumor aggressiveness, when this axis was damaged with a caspase-1 inhibitor, TAMs cells suffered a specific commitment that negatively affected tumor progression." (PMID 29966227, 2018). "Caspase recruitment domain-containing protein (CARD) 8, also known as TUCAN (tumor upregulated CARD-containing antagonist of caspase nine), interacts physically with caspase-1 and negatively regulates caspase-1-dependent IL-1β expression and nuclear factor- (NF-) κB activation." (PMID 30140708, 2018). "Since activated caspase-1 form was only detectable in TAMs but not tumor cells or normal tissues, caspase-1 inhibition will be relatively specific for TAMs." (PMID 28974683, 2017). "Mechanistically, these pseudoviruses activate the NLRP3 and AIM2 inflammasomes, leading to caspase-1-mediated tumour regression that is dependent on neither cytotoxic T lymphocytes nor humoral immune response." (PMID 28397782, 2017). "Together, these results indicate that caspase-1-mediated non-IL-1/IL-18 pathway(s) is likely to drive PsV-induced tumour regression." (PMID 28397782, 2017). "In addition to adhesion and transmigration, stimulation of both MDA-MB-231 and MCF7 tumour cells with IL-1β increased their migratory ability; furthermore, this increase was also observed with macrophage conditioned media and could be inhibited with a caspase-1 inhibitor." (PMID 28551814, 2017). "We found that tumour-infiltrating CD11b+ myeloid cells from DIO mice had increased CASP1 processing but neither in CD11b+ cells from ND tumours nor in CD11b− cells." (PMID 27708283, 2016). "In particular, the activation of NLRP3 inflammasome via TLR4 signalling led to IL-1β release after caspase-1 activation, whereas, the activation of caspase-11 was important for both IL-1α release and NLRP3-dependent IL-1β release in the lung of tumor-bearing mice." (PMID 27528423, 2016). "This literature and our results together suggest that the inhibitory effects of Flii on caspase-1 activation and apoptosis may aid SCC tumor evasion in FliiTg/Tg mice." (PMID 26497552, 2015). "In a separate experiment we noted that NK cells from CASP-1-KO mice were less cytotoxic towards tumor cells (data not shown)." (PMID 25268644, 2014). "A possible explanation for this discrepancy is that while it has been reported that Bet A activates both caspase-8 and caspase-3 in different tumor cells no Bet A-mediated activation of caspase-1 has been described." (PMID 23166834, 2012).
tumor (continued). "While activation of pyroptosis-related genes (e.g., CASP1, GSDMD) enhances inflammation and attracts immune cells, it may paradoxically promote tumor progression by allowing HCC cells to escape immune surveillance through modulation of apoptosis-inducing factors." (PMID 40018411, 2025). "Similarly, ZIF-8 nanoparticles induce pyroptosis through a caspase-1- GSDMD-dependent pathway, triggering a tumor immune response and reprogramming the tumor's immunosuppressive microenvironment (TME) to effectively inhibit tumor growth." (PMID 39994107, 2025). "After 12 h post-seeding, statistically increased levels of caspase-1 were observed in contact with GF + PTX compared with GF (p < 0.0001) and GFAP + PTX compared with GFAP (p < 0.0001), suggesting the anti-tumor and pro-inflammatory properties of PTX in contact with metabolically active tumor cells." (PMID 39940603, 2025). "When the tumor was irradiated, pyroptosis was induced by activated caspase-1 cleavage of GSDME, which significantly increased the production of ROS, and the levels of TNF-α and IFN-γ were significantly elevated, promoting the death of tumor cells by T cells and other killer immune cells." (PMID 40698137, 2025). "We first compared the differences in protein expression of BAX, CASP1, CASP8 and PYCARD in renal clear cells by CPTAC database, and the results showed that the protein levels of BAX, CASP1, CASP8 and PYCARD were significantly higher than those in normal tissues in tumor cells." (PMID 38439022, 2024). "The in vivo experiments indicated that butyrate could reverse the aggravation of intestinal inflammation and the accelerated tumor growth induced by HFD-FMT, and the NLRP3/Caspase-1 pathway in the colon activated by HFD-FMT was also significantly inhibited by butyrate." (PMID 37781523, 2023). "Selenium plays an important role in increasing the expression levels of Caspase-1, Caspase-3, Caspase-8, and Caspase-9 and decreasing the expression levels of Bcl-2 and LC3, which promote the development of cellular pyroptosis and apoptosis and increase the rate of tumor cell death." (PMID 37994159, 2023). "In addition, treatment with exogenous butyrate reversed the M1 polarization of proinflammatory macrophages, aggravation of intestinal inflammation, and accelerated tumor growth induced by HFD; the NLRP3/Caspase-1 pathway activated by HFD in the colon was also significantly inhibited." (PMID 37781523, 2023). "In addition, our study suggests that 17β-estradiol may be effective in HCC treatment as it can inhibit tumor cell growth and proliferation by activating the NLRP3 inflammasome and the caspase-1-dependent pyroptosis in HCC cells." (PMID 36763290, 2023). "Moreover, the addition of EI-NP enhanced the pyroptosis as evidenced by the increased generation of tumor antigen HMGB1 but did not alter the expression of cleaved caspase 1 or cleaved GSDMD." (PMID 36280674, 2022). "Protrusions facilitate lysosomal rupture, following which the tumor overexpressed glutathione (GSH) triggers the degradation of VPTA to release Mn ions and IONPs for rapid and persistent ROS generation, which synergistically activates the NLRP3/caspase-1/GSDMD signaling pathway for pyroptosis." (PMID 35673561, 2022). "Collectively, it was demonstrated here that VNP-GD could efficiently trigger tumor cell pyroptosis by the combination of enhancing intracellular delivery of GSDMD via VNP and further activation of N-terminal GSDMD mediated by VNP-induced caspase 1 cleavage." (PMID 36280674, 2022). "In addition, normal spleen Treg, normal tissue Treg, non-tumor diseased spleen Treg, non-tumor diseased tissue Treg, tumor spleen Treg and tumor Treg had 2, 13, 9, 11, and 12 specific upregulated caspase-1 secretomic pathways, respectively." (PMID 34084175, 2021).